TBRG4 (transforming growth factor beta regulator 4)
Description:
Plays a role in processing of mitochondrial RNA precursors and in stabilization of a subset of mature mitochondrial RNA species, such as MT-CO1, MT-CO2, MT-CYB, MT-CO3, MT-ND3, MT-ND5 and MT-ATP8/6. May play a role in cell cycle progression.
Synonyms: CPR2; FASTKD4; KIAA0948; H_TD2522F11.8
Tractability: PROTAC: ubiquitination databases record sites on it; its protein half-life has been measured.
Gene: Protein-coding gene on chromosome 7 (45,097,584 to 45,112,048, reverse strand). Ensembl gene ENSG00000136270.
Subcellular location: Mitochondrion matrix
Subcellular location (Human Protein Atlas): Mitochondria
Pathways (Reactome):
Metabolism of RNA: FASTK family proteins regulate processing and stability of mitochondrial RNAs
Gene Ontology:
Molecular function: protein binding; RNA binding
Biological process: mitochondrial mRNA processing; mRNA metabolic process; regulation of mitochondrial mRNA stability; mitochondrial RNA processing; positive regulation of cell population proliferation; regulation of cell cycle
Cellular component: mitochondrial matrix; mitochondrion; ribonucleoprotein granule
Genetic constraint (gnomAD): Loss-of-function variants: 43 observed, 67.23 expected, observed/expected ratio (o/e) 0.64, 90% interval 0.5 to 0.82. The upper end of that interval is the gene's LOEUF score, 0.82, which puts it in group 3 of 6, group 1 being the genes least tolerant of losing a copy. Missense variants: 709 observed, 817.07 expected, observed/expected ratio (o/e) 0.87, 90% interval 0.81 to 0.92. Synonymous variants: 366 observed, 354.5 expected, observed/expected ratio (o/e) 1.03, 90% interval 0.95 to 1.13.
Homologues: Orthologues: chimpanzee TBRG4 (99% identical), macaque TBRG4 (91% identical), pig TBRG4 (78% identical), rat Tbrg4 (77% identical), dog TBRG4 (76% identical), mouse Tbrg4 (76% identical), rabbit TBRG4 (75% identical), guinea pig TBRG4 (71% identical), tropical clawed frog tbrg4 (47% identical), zebrafish tbrg4 (40% identical), Caenorhabditis elegans fask-1 (15% identical). Paralogues in human: FASTKD3 (20% identical), FASTK (18% identical), FASTKD1 (18% identical), FASTKD5 (18% identical), FASTKD2 (16% identical).
Diseases named in the same sentence as TBRG4 in open-access papers:
TBRG4 is named in the same sentence as 43 diseases in open-access papers, as found by Europe PMC text mining. Sharing a sentence is not in itself a finding about the gene and the disease. The quoted sentences say what the papers report.
lung carcinoma (4 papers, 2019 to 2025). "Transforming growth factor β regulator 4 (TBRG4) is upregulated in lung cancer, but its biological role and underlying mechanisms remain poorly understood." (PMID 40260662, 2025). "Nonetheless, further research is necessary to fully elucidate the molecular mechanisms underlying TBRG4’s role in lung cancer and to assess its viability as a therapeutic target, particularly in the contexts of immunotherapy and cancer metabolism." (PMID 40260662, 2025). "Suppressing TBRG4 expression appears to inhibit lung cancer progression by modulating the cell cycle and EMT pathways, while also potentially affecting immune responses and mitochondrial function." (PMID 40260662, 2025). "By conducting co-expression analysis, pathway enrichment analysis, and validating results via western blotting, we aim to elucidate the molecular mechanisms through which TBRG4 contributes to lung cancer progression." (PMID 40260662, 2025). "Our previous research identified significantly elevated TBRG4 protein levels in lung cancer tissues compared to normal tissues, suggesting its involvement in critical pathways such as cell cycle regulation." (PMID 40260662, 2025). "To investigate TBRG4’s role in lung cancer progression, we assessed cell proliferation, colony formation, and cell cycle alterations in lung cancer cells following TBRG4 knockdown." (PMID 40260662, 2025). "In conclusion, our findings highlight the critical role of TBRG4 in lung cancer prognosis and tumorigenesis." (PMID 40260662, 2025). "TBRG4 knockdown significantly inhibited cell proliferation and colony formation while inducing cell cycle arrest and apoptosis in lung cancer cells." (PMID 40260662, 2025). "Future studies using orthotopic lung cancer models or syngeneic immunocompetent systems would better reflect TBRG4’s role in tumor–stroma interactions and responses to immunotherapy." (PMID 40260662, 2025). "In our previous study, we observed a significant increase in TBRG4 expression in lung cancer tissues compared to normal controls." (PMID 40260662, 2025). "We first assessed TBRG4 protein expression levels in four lung cancer cell lines (H1688, H1975, H1299, and A549) and one normal human lung epithelial cell line (BEAS-2B)." (PMID 40260662, 2025). "Genes with a Pearson correlation coefficient above 0.4 with TBRG4 in lung cancer were identified via UALCAN, followed by pathway enrichment analyses to explore their functional associations." (PMID 40260662, 2025). "TBRG4 plays an important role in the progress of many cancers, including oral squamous cell carcinoma, lung cancer, osteosarcoma, and colorectal cancer." (PMID 38347489, 2024). "RRM2 is regulated by the transforming growth factor beta regulator 4 (TBRG4) gene which affects tumorigenesis in human H1299 lung cancer cells." (PMID 31886214, 2019). "Collectively, these findings suggest that TBRG4 may serve as a promising prognostic biomarker and therapeutic target in lung cancer." (PMID 40260662, 2025). "To further explore the relationship between TBRG4 expression and immunotherapy responses in lung cancer, we evaluated whether TBRG4 could serve as a predictor of patient outcomes following ICI therapy." (PMID 40260662, 2025). "TBRG4 may represent a potential therapeutic target, and interventions aimed at inhibiting its function could help suppress lung cancer growth and progression." (PMID 40260662, 2025). "Given the growing importance of immunotherapy in lung cancer treatment, further investigation into TBRG4’s role in immune checkpoint regulation and its interaction with the tumor immune microenvironment could uncover novel therapeutic strategies." (PMID 40260662, 2025). "TBRG4, the most stably expressed gene in “Q”, was reported as being actively involved in myeloma, squamous carcinoma, osteosarcoma, glioblastoma, leukemia and lung cancer." (PMID 35723406, 2022).
hepatocellular carcinoma (3 papers, 2024 to 2025). A malignant tumor that arises from hepatocytes. "TBRG4 promotes hepatocellular carcinoma progression by inhibiting ferroptosis through the DDX56/p-AKT/GSK3β pathway and binding to Beclin1, while its knockdown reduces tumor cell proliferation, migration, and invasion." (PMID 39315094, 2024). "Next, we use the “RMS” package to build nomogram related models and Calibration analysis and found that TBRG4 can accurately predict the survival prognosis of hepatocellular carcinoma patients." (PMID 38347489, 2024). "utilized transwell, wound healing, and CCK8 assays to demonstrate that knocking down TBRG4 significantly inhibits the migration, invasion, and proliferation of hepatocellular carcinoma (HCC) cells." (PMID 40808964, 2025). "In this study, it was determined that the mitochondrial metabolic gene TBRG4 serves as a significant promoter of hepatocellular carcinoma (HCC) proliferation and functions as an independent prognostic marker." (PMID 38347489, 2024). "However, the specific role of TBRG4 in hepatocellular carcinoma (HCC) remains unclear." (PMID 38347489, 2024).
melanoma (3 papers, 2020 to 2025). A malignant, usually aggressive tumor composed of atypical, neoplastic melanocytes. "Among these kinases, 6 (RPS6KB2, DSTYK, TBRG4, CDK4, POLR2E, FASTKD5) and 4 (STK26, PAK1, EPHB2 and JAK3) were consistently up- or down-regulated, respectively, in the metastatic lines of at least two pairs of melanoma cells." (PMID 32051510, 2020).
multiple myeloma (3 papers, 2016 to 2025). "TBRG4 has previously been implicated in multiple myeloma, oral squamous cell carcinoma, and breast cancer, where it functions as an oncogene." (PMID 40260662, 2025). "Additionally, TBRG4 has been associated with multiple myeloma, underscoring its potential role in tumorigenesis." (PMID 40260662, 2025). "High expression of transforming growth factor beta regulator 4 (TBRG4) correlates with poor outcome for multiple myeloma patients." (PMID 27223260, 2016).
osteosarcoma (3 papers, 2022 to 2025). A usually aggressive malignant bone-forming mesenchymal neoplasm, predominantly affecting adolescents and young adults. "Functional studies demonstrate that TBRG4 knockdown inhibits osteosarcoma cell proliferation, clonogenic ability, and invasion, while inducing apoptosis in vitro; in vivo, it suppresses tumor growth and metastasis." (PMID 40808964, 2025). "In addition, TBRG4 is abnormally overexpressed in osteosarcoma and esophageal squamous cell carcinoma, and can regulate cell proliferation and invasion through PI3K/AKT." (PMID 38347489, 2024). "Moreover, TBRG4’s consistent pro-tumorigenic role across osteosarcoma, pancreatic cancer, HCC, and now LUAD suggests it is a conserved oncogenic factor, warranting broader oncology research, and further validates the robustness of BREGI as a functionally coherent gene set." (PMID 40808964, 2025).
breast carcinoma (2 papers, 2025). "Previous studies have identified TBRG4 as an oncogene in breast cancer, where its deficiency inhibits tumor cell migration and proliferation by promoting apoptosis." (PMID 40260662, 2025).
colorectal cancer (2 papers, 2022 to 2024). A primary or metastatic malignant neoplasm that affects the colon or rectum. "In doing so, we find that both rs4724362 and rs73109897 (which both appear to act through TBRG4 on sites around the MT-TE and MT-CYB junction) are in LD with rs12672022, which is associated with colorectal cancer." (PMID 35869520, 2022).
liver cancer (2 papers, 2024 to 2025). An epithelial or non-epithelial malignant neoplasm that arises from the liver. "To further validate the expression of TBRG4 in HCC, we used Western blot and RT-PCR to detect the expression level of TBRG4 in liver cancer cell lines." (PMID 38347489, 2024).
pancreatic cancer (2 papers, 2025). "Furthermore, its role in pancreatic cancer cells is similar, as knocking down TBRG4 has been shown to inhibit the migration, invasion, and epithelial-mesenchymal transition (EMT) of pancreatic cancer." (PMID 40808964, 2025).
acute myeloid leukemia (1 paper, 2025). Acute myeloid leukemia (AML) is a group of neoplasms arising from precursor cells committed to the myeloid cell-line differentiation. "Conversely, TBRG4 expression was downregulated in acute myeloid leukemia, ovarian cancer, prostate cancer, and thyroid cancer." (PMID 40260662, 2025).
Burkitt lymphoma (1 paper, 2022). A rare form of malignant mature B-cell non-Hodgkin lymphoma. "A similar phenotype was observed in Akata-BX1 Burkitt lymphoma cells, where the expression of EBV genes was also increased in TBRG4-depleted cells compared to NTC-treated cells." (PMID 36417478, 2022).
Non-alcoholic fatty liver disease (1 paper, 2024). "The enrichment analysis results of GO and KEGG indicate that TBRG4 may be related to Non-alcoholic fatty liver disease, Oxidative phosphorylation, structural constituent of ribosome, NADH dehydrogenase (ubiquinone) activity." (PMID 38347489, 2024).
cancer (8 papers, 2020 to 2025). A tumor composed of atypical neoplastic, often pleomorphic cells that invade other tissues. "The overexpression of FASTKD4/TBRG4 in different types of cancer is highly associated with cancer progression." (PMID 34827720, 2021). "TBRG4 has been implicated in various diseases, including cancer." (PMID 40260662, 2025). "Our results indicated that TBRG4 was expressed at significantly higher levels in cancer cells compared to the normal control." (PMID 40260662, 2025). "Novel DNA methylation biomarkers for the prognosis during the early stages of cancer, such as INHBB, SMOC2, BDNF, and TBRG4, are being tested for clinical use to improve detection methods and guide the treatment and diagnoses of cancer patients." (PMID 34827720, 2021). "Even though the relevance of these two snoRNAs has not yet been reported, different groups have reported alterations in SNHG11 and TBRG4 in different cancer types." (PMID 32046192, 2020). "To determine whether TBRG4 knockdown selectively affects cancer cells, we also assessed its impact on the normal lung epithelial cell line BEAS-2B." (PMID 40260662, 2025). "This supports the idea that TBRG4 plays a more selective role in cancer cells." (PMID 40260662, 2025). "Metabolic profiling of TBRG4-depleted cells may help elucidate this potential link, bridging its molecular functions with cancer cell adaptability." (PMID 40260662, 2025). "Moreover, the link between TBRG4 and mitochondrial function adds another layer of complexity to understanding its role in cancer." (PMID 40260662, 2025). "In addition, TBRG4 knockdown significantly increased the apoptosis rate in both cancer cell lines." (PMID 40260662, 2025). "In addition, our expression analysis identified two snoRNA/host gene couples (SNORA71E/SNHG11 and SNORA5C/TBRG4) which are transversally up-regulated in different cancer series, indicating that they may have a role in cellular mechanisms of tumorigenesis." (PMID 32046192, 2020). "In addition to its role in cell cycle regulation, pathway analysis of co-expressed genes links TBRG4 to EMT, a key process in cancer metastasis." (PMID 40260662, 2025). "Upon FASTKD4 depletion, the MT-ND5-CYB precursor accumulates, accompanied by a decrease insome mature transcript levels, including MT-ND5 and MT-CYB.The exact mechanism of TBRG4 in cancer is still under constant research." (PMID 36518140, 2022). "TBRG4, the GMR of “Q”, was upregulated in “P” (x = 1.25, WIR = 0.46) and “Q” (x = 1.73, WIR = 1.39) but not in “M”, while TMEM186, the GMR of “M”, was not regulated in any of the profiled cancer nodules." (PMID 35723406, 2022).
tumor (7 papers, 2020 to 2025). "Bioinformatics analysis revealed that TBRG4 was abnormally highly expressed in HCC tumor tissues and was associated with poor prognosis and metastasis in HCC patients." (PMID 38347489, 2024). "TBRG4 is highly expressed in HCC tumor tissues and is associated with poor prognosis." (PMID 38347489, 2024). "Mechanistically, TBRG4 promotes tumor invasiveness through activation of the PI3K/AKT pathway and contributes to chemotherapy resistance by enhancing DNA repair capacity." (PMID 40260662, 2025). "The average tumor weight in the shTBRG4#2 group was significantly lower than in the control group, confirming a strong inhibitory effect of TBRG4 knockdown on tumor growth." (PMID 40260662, 2025). "Taken together, these results indicate that silencing TBRG4 effectively inhibits tumor growth in vivo." (PMID 40260662, 2025). "The consistent findings across both physical measurements and imaging data underscore the potential of TBRG4 as a therapeutic target for suppressing tumor progression." (PMID 40260662, 2025). "Mice injected with TBRG4 knockdown cells (shTBRG4#2 group) exhibited significantly reduced tumor growth compared to controls." (PMID 40260662, 2025). "Next, we established xenograft lung tumor models using BALB/c nude mice to evaluate the impact of TBRG4 knockdown on tumor growth in vivo." (PMID 40260662, 2025). "Multivariate analysis showed that only TBRG4 and tumor status were prognostic factors for HCC patients." (PMID 38347489, 2024). "Western blot and RT-PCR confirmed a significant increase in protein and mRNA levels of TBRG4 in tumor tissue." (PMID 38347489, 2024). "Univariate analysis showed that the prognosis of patients was related to the T/M staging, pathological grade, TBRG4 expression level, and tumor status." (PMID 38347489, 2024). "Studies have demonstrated a significant increase in TBRG4 expression in patients with head and neck squamous cell carcinoma and in the tumor tissues of multiple myeloma patients with extramedullary recurrence." (PMID 38347489, 2024). "Understanding how TBRG4 drives tumor growth and progression could pave the way for developing targeted therapies that improve early diagnosis and enhance treatment efficacy." (PMID 40260662, 2025). "Additionally, TBRG4 expression was positively correlated with tumor stage, and higher expression levels were associated with poorer prognosis in LUAD patients (HR ═ 1.72, 95% CI: 1.186–2.506, log-rank P ═ 0.004)." (PMID 40260662, 2025). "Whether TBRG4 intersects with mitochondrial metabolism to fuel tumor progression remains an open question." (PMID 40260662, 2025). "This shift in protein expression patterns implies that TBRG4 may regulate the balance between epithelial and mesenchymal phenotypes, potentially influencing tumor invasiveness and metastatic potential." (PMID 40260662, 2025). "In addition, we collected some HCC tumor tissues and adjacent tissues for immunohistochemical staining, and the results showed a significant increase in the proportion of TBRG4 positive cells in tumor tissues." (PMID 38347489, 2024). "This suggests that TBRG4 may participate in the proliferation and migration of tumor cells through the DDX56/p-AKT/GSK3β signaling pathway." (PMID 38347489, 2024). "Beyond its impact on LUAD progression, TBRG4 may also modulate the tumor immune microenvironment." (PMID 40260662, 2025). "Our experimental assays confirmed that TBRG4 depletion reduces EMT marker expression and suppresses tumor growth in vivo." (PMID 40260662, 2025). "The results showed that TBRG4 was significantly elevated in Hep3B, Huh7, SMC7721, and HepG2 tumor cells, while its expression was lower in human normal liver epithelial cells LO2." (PMID 38347489, 2024).
tumor (continued). "For instance, SNORA71E/SNHG11 is in the top 10 of over-expressed targets in all tumor types, SNORA72/RPL30 is in the top 10 for all tumor types but KIRCs and OVs, and SNORA5C/TBRG4 is only missing in UCECs, OVs, and GBMs shortlists." (PMID 32046192, 2020). "Although our study did not directly examine TBRG4’s role in metabolism, the observed reduction in tumor growth following TBRG4 depletion raises the possibility of its involvement in metabolic reprogramming." (PMID 40260662, 2025). "Similarly, in the tumor cohorts of GSE14520 and ICGC, the expression level of TBRG4 also showed a significant increase." (PMID 38347489, 2024). "Furthermore, TBRG4 depletion reduced EMT marker expression and suppressed tumor growth in vivo." (PMID 40260662, 2025). "Conversely, TBRG4 showed a negative correlation with CD96 and TNFSF15 (P < 0.05, R < −0.1), suggesting it may influence pathways that inhibit T cell function, thereby fostering a more immunosuppressive tumor microenvironment." (PMID 40260662, 2025).
TBRG4 also shares sentences with these, for which no sentence is quoted: glioblastoma (2 papers); glioma (2); oral squamous cell carcinoma (2); Alzheimer disease (1); amyotrophic lateral sclerosis (1); bile duct cancer (1); bladder cancer (1); cervical cancer (1); colon cancer (1); dyslipidemia (1); esophageal cancer (1); head and neck cancer (1); infection (1); kidney (1); kidney clear cell carcinoma (1); leukemia (1); leukoplakia (1); lung adenocarcinoma (1); lung squamous cell carcinoma (1); neurodegenerative disease (1); ovarian carcinoma (1); Parkinson disease (1); prostate carcinoma (1); rectal cancer (1); squamous carcinoma (1); stomach cancer (1); testicular cancer (1); thyroid cancer (1); uterine carcinosarcoma (1).